CCR2 (C-C motif chemokine receptor 2)
Diseases named in the same sentence as CCR2 in open-access papers (continued):
Sharing a sentence is not in itself a finding about the gene and the disease.
breast cancer (continued). "CCR2-induction of enzyme protein levels represents one, but likely not the only mechanism for regulation of glycolysis in breast cancer cells." (PMID 35405500, 2022). "Furthermore, we found that, in breast cancer, the expression of three typical markers of TAMs (CD86, CSF1R, and CCR2) were positively correlated with SIPA1 and MYH9, respectively." (PMID 35453742, 2022). "CCR2 antagonists have been found to suppress hepatocellular carcinoma growth, reduce lung metastasis from LLC tumours and liver metastases from colorectal or breast cancer xenografts in animal models." (PMID 36241867, 2022). "Additionally, in vitro studies have demonstrated that CCL2/CCR2 mediated p42/44MAPK and SMAD3 pathways in breast cancer cells are important in growth, survival, migration and invasion." (PMID 33888841, 2021). "To determine the clinical relevance of CCL2/CCR2 signaling protein expression in breast cancer, we performed immunohistochemistry staining on patient samples of DCIS, IDC and normal adjacent tissues for detection of CCL2, CCR2, phospho-SMAD3 and phospho-42/44MAPK proteins." (PMID 33888841, 2021). "In a study dissecting the origin of TAM, the TAM percentage in CCR2-/- mice in the MMTV-PyMT (PyMT) mammary tumor model was found not to be significantly different compared to WT controls." (PMID 34804061, 2021). "We chose genes that encode proteins that regulate T cell activation or differentiation, such as PD-L2, Gal9, CD86, CXCR3, CCR2, which have not yet been investigated in canine mammary cancers." (PMID 32225066, 2020). "In parallel, CCL2 activities via CCR2, as well as CCL5-induced signaling were demonstrated to contribute to increased EMT and twist expression, at times accompanied by increased tumor cell invasion in breast cancer cells." (PMID 32582148, 2020). "In summary, these data indicate that ALDH1A1 is important for CCL2/CCR2-mediated breast cancer cell growth, but not invasion." (PMID 31208996, 2019). "Our studies indicate that HTRA2 is important in CCL2/CCR2-mediated breast cancer cell growth and invasion, but not apoptosis." (PMID 31208996, 2019). "Here, CCL2 stimulation of CCR2 overexpressing cells enhanced growth and invasion more than CCR2 overexpression alone, further supporting an important role for paracrine CCL2/CCR2 signaling to breast cancer cells." (PMID 31208996, 2019). "Our present study also examined the regulatory effects of CCL2 on different breast cancer cells, while disrupting CCL2-CCR2 axis by CCR2 antagonist RS102895 could attenuate these effects partially due to downregulation of MMP-9 and VEGF expression in vitro." (PMID 29934505, 2018). "Expression of HO-1 did not correlate with levels of CCR2, a macrophage receptor, which allows for monocyte recruitment into tumors and metastatic spread of breast cancer in mice models as well as marker of M1 polarization." (PMID 26418896, 2015). "Namely, increased CCL2 level in the tumor by doxorubicin treatment promotes CCR2 dependent monocyte recruitment, although the PyMT mammary tumors normally recruit monocytes/macrophages via CCR6 but not CCR2." (PMID 26275794, 2015). "This is consistent with the previous findings that human breast cancer cells also do not express CCR2." (PMID 23527025, 2013). "Interestingly, targeting of CCR2 and MET resulted in the highest reduction in growth of mammary carcinomas, corresponding to a significant increase in cancer cell apoptosis, decreased cellular proliferation, as well as reduced stromal reactivity and inflammation in the microenvironment." (PMID 40736024, 2025). "Moreover, in addition to promoting tumor cell extravasation via local release of VEGF-A, CCR2-expressing monocytes give rise to immune-suppressive MAM-precursors that exhibit resistance to CSF-1 blockade and promote pulmonary seeding of mammary carcinoma cells." (PMID 33924237, 2021).
breast cancer (continued). "Thus, it might be an effective combinatorial treatment with PARP1 and CCR2 inhibitors to achieve better outcomes where CCL2 levels are determined to be high, particularly in breast cancer, as well as other solid tumors." (PMID 32455851, 2020). "Therefore, the use of CCL2 siRNA, CCR2 siRNA, CCL2-neutralizing antibodies, CCL2 inhibitors or CCR2 antagonists has given promising results in the therapy of cancers such as breast cancer, glioma, and hepatocellular cancer in laboratory animals inoculated with cancer cells." (PMID 33182504, 2020). "In addition, in breast cancer lung metastasis mouse models, CCL-2 secreted by both tumor cells and endothelial cells preferentially recruited C-C chemokine receptor type 2 (CCR2+) macrophages to lungs, resulting in increased metastatic seeding and tumor outgrowth." (PMID 31130637, 2019). "Indeed, in the MMTV-PyMT mouse model of spontaneous breast cancer, CCL2, released by either tumor cells or stromal cells at the metastatic lung niche, induces the recruitment of CCR2-expressing iMo, which in turn favor the extravasation of tumor cells, through the release of VEGFA." (PMID 31447834, 2019). "However, the contributions of ALDH1A1 and HTRA2 to breast cancer cell growth and invasion may depend on a complex set of factors involving differences in CCL2/CCR2 signaling among breast cancer cell lines." (PMID 31208996, 2019). "Therefore, we examined whether the presence of mammary carcinomas affects the development and deployment of CD45–CD117/c-Kit+Flk1/Vegfr2+ EPCs and whether CCL2 and CCR2 play a role." (PMID 27820834, 2016). "As shown in triple-negative patient-derived xenograft (PDX) models of breast cancer, pre-metastatic CCL2 niches are enriched in IFNγ-producing CCR2+ monocytes only in nonmetastatic areas." (PMID 40427136, 2025). "To date, a functional connection between CCR2 and MET in breast cancer has not been clearly identified." (PMID 35405500, 2022). "Modulating HTRA2 expression in CCR2-H SUM225, CCR2-KO and parental DCIS.com cells led to changes in spheroid size and PCNA expression, indicating that HTRA2 exerts important effects on breast cancer cell growth regardless of cell line or CCR2 status." (PMID 31208996, 2019). "Altering ALDH1A1 expression in CCR2-H SUM225, CCR2-KO and parental DCIS.com cells led to changes in spheroid size and PCNA expression, indicating that an important role for ALDH1A1 in breast cancer cell growth regardless of cell line or CCR2 status." (PMID 31208996, 2019). "Recent studies have indicated that CCR2, but not CCL2, regulates CCL2-induced breast cancer cell survival and motility through MAPK- and Smad3-dependent mechanisms." (PMID 28424406, 2017). "Although CD163+ MØs, CCL2 and CCL7 are associated with cancer metastasis and poor prognosis and high CCL2 levels are found in various cancer types, including breast cancer and some NSCLC31–33, blocking the CCL2/CCR2 axis alone does not impede tumors from recruiting monocyte-origin resident MØs5." (PMID 38076998, 2023).
atherosclerosis (153 papers, 2005 to 2026). A disease characterized by the build-up of fatty material and calcium deposition in the arterial wall resulting in partial or complete occlusion of the arterial lumen. "One of the most critical functions of CCR2 is its involvement in controlling microbial infections and tissue repair; however, it is also associated with pathological conditions such as atherosclerosis, fibrosis, and cancer." (PMID 40909274, 2025). "CCR2-deficient mice exhibit significantly decreased monocyte recruitment during peritonitis, autoimmune encephalitis, tuberculosis, and atherosclerosis." (PMID 38454505, 2024). "In this context, it has recently been shown that the impact of CCR2+ monocyte subpopulations even reveals sexual dimorphism, where boys seem to be at higher atherosclerosis risk than girls." (PMID 36921085, 2023). "Several chemokine receptors and their ligands such as CCR2 and MCP-1 have been well-characterized to have pro-atherogenic effects in vivo, and deficiency of CCR2 also led to decreased atherosclerosis in animal models." (PMID 33459922, 2022). "Cardiovascular studies have demonstrated higher expression of CCL2/CCR2 increased the risk for higher platelet response, atherosclerosis, and thrombus formation." (PMID 35749425, 2022). "Studies in animal models and human adults show that CCR2 expression in monocytes is associated with increased arterial wall inflammation and atherosclerosis progression, where males exhibit more robust CCR2 expression than females." (PMID 36286282, 2022). "CCR2 is necessary for the development of atherosclerosis, as it has been demonstrated in murine models of atherosclerosis where either the CCR2 gene or the CCL2 gene, encoding for one of its ligands, are inactivated." (PMID 35711383, 2022). "The CCR2+ classical monocyte percentage was 14.7 ± 9.47% higher in male obese children with subclinical atherosclerosis risk than in boys with IMT < p75 (p = 0.039)." (PMID 36286282, 2022). "Several monoclonal antibodies for CCR2 are under development to treat cardiovascular disease caused by atherosclerosis, one famous star of which is MLN-1202." (PMID 34345249, 2021). "Although the phenotypes of CCL2- and CCR2-deficient mice are concordant in models of inflammatory disease such as atherosclerosis or experimental allergic encephalitis, they differ in other settings." (PMID 27820834, 2016). "A pathogenic role of CCR2 in atherosclerosis has been clearly established through evidence of a sustained reduction in atherosclerotic lesions in ccr2-deficient mice." (PMID 27458015, 2016). "CCR2-deficient mice on an atherosclerosis-prone background did, however, result in a significantly reduced lesion size in mice." (PMID 26257740, 2015). "Ly6Clow monocytes were suggested to contribute to tissue repair in the myocardium, and, in contrast to Ccr2-deficient mice, Nr4a1-deficient mice showed increased atherosclerosis." (PMID 23582326, 2013). "A number of recent studies have looked at the association of the CCR2 Val64Ile polymorphism and clinical endpoints associated with atherosclerosis." (PMID 20181074, 2010). "Using a slightly different approach Rollins and colleagues have demonstrated that CCL2, the ligand for CCR2, plays an equally important role in the development of atherosclerosis in low-density lipoprotein receptor deficient mice." (PMID 16259633, 2005). "The CCR2 receptor has been shown to be causally involved in the generation of atherosclerosis in mouse knockout models, and at the genetic level, single‐nucleotide polymorphisms in the reading frame of CCR2 have been associated with an increased risk of myocardial infarction." (PMID 37927302, 2023). "Given the potential role of the CCR2 chemokine receptor in progression of atherosclerosis, the hypothesis that genetic variants that could affect function of the receptor and its ligands could represent a risk factor in this setting was explored." (PMID 35711383, 2022).
atherosclerosis (continued). "Since CCR2 is associated with atherosclerosis progression, the high affinity towards CCR2 could provide the platform for both diagnosis and therapeutics of atherosclerosis." (PMID 33799932, 2021). "Genetic knockout of CCR2 (CCR2−/−) in the Apolipoprotein E-deficient (apoE−/−) mouse model of atherosclerosis resulted in a significant decrease in lesion size compared to apoE−/− controls, which was caused by a reduction in monocyte/macrophage recruitment to the atherosclerotic lesion." (PMID 28246398, 2017). "Recently, a phase II clinical trial using a CCR2 neutralizing antibody MLN1202 found a decrease in C-reactive protein in patients with high risk of atherosclerosis, suggesting the potential for the suppression of inflammation, plaque angiogenesis and ultimately plaque progression." (PMID 27834814, 2016). "Based on the adoptive transfer study and the fact that CCR2-deficient mice show reduced circulating monocyte counts, it can be suggested that the beneficial effect on atherosclerosis is due to its effects on monocyte release from the bone marrow, rather than directs effects on monocyte recruitment." (PMID 26257740, 2015). "In addition, CCR2-deficient animals ex decreased susceptibility to atherosclerosis and decreased intimal hyperplasia following arterial injury." (PMID 24816562, 2014). "It is also believed that Ly6C+ monocytes play a role in chronic inflammation, such as the formation of the atherosclerotic plaque, because Ccr2-deficient mice on low density lipoprotein receptor- or apolipoprotein E-deficient backgrounds and a high-fat diet have decreased atherosclerosis." (PMID 23582326, 2013). "Development of atherosclerosis (induced by a variety of means) has been shown to be attenuated in mice made deficient in adhesion molecules like P- and E-selectins or deficient in the chemokine receptor CCR2." (PMID 18560564, 2008). "CCR2 is believed to mediate extravasation of blood monocytes to the sites of inflammation and is implicated in the pathogenesis of several inflammatory diseases such as rheumatoid arthritis, multiple sclerosis and atherosclerosis." (PMID 16001983, 2005). "This process could be similar to the protective effect of Ccl2 and Ccr2 deficiencies for the formation of atherosclerosis that lead to a reduction of the formation of foam cells due to a reduced recruitment of systemic myeloid cells to the site of the lesion in the periphery." (PMID 22545116, 2012). "CC-family chemokine receptor 2 (CCR2) is implicated in the trafficking of blood-borne monocytes to sites of inflammation and is implicated in the pathogenesis of several inflammatory diseases such as rheumatoid arthritis, multiple sclerosis and atherosclerosis." (PMID 16001983, 2005). "The addition of anti-CCR2 to antimicrobial therapy dampened monocyte activation and atherosclerosis development." (PMID 41987917, 2026). "Despite the lack of data from clinical trials targeting CCR2 in patients with cardiovascular disease, studies in experimental models of atherosclerosis have provided supportive evidence for an atheroprotective effect of pharmacologically targeting CCR2." (PMID 40119478, 2025). "MDM were reported to infiltrate into lesions from peripheral blood in ischaemic stroke and atherosclerosis, and C-C chemokine receptor (CCR2) is often used as a major marker of MDM." (PMID 40221393, 2025). "In murine atherosclerosis, SerBut reduced total immune cells, monocytes, and CCR2+ monocytes in the aorta compared with water-treated controls." (PMID 40779455, 2025). "The CCL2-CCR2 axis, formed by the binding of CCR2 with CCL2, is associated with the progression of various diseases, such as atherosclerosis, diabetes, and cancer." (PMID 40535169, 2025). "Ultimately, only clinical testing can provide evidence in favor of or against pharmacological targeting of CCR2 for patients with atherosclerosis." (PMID 37645892, 2024).
atherosclerosis (continued). "In animal models of atherosclerosis, propagermanium inhibits macrophage infiltration by blocking the CCR2 function." (PMID 39125901, 2024). "The endogenous murine CCR2 gene was substituted with human CCR2 in an animal model of atherosclerosis fed a Western diet and given angiotensin II infusion." (PMID 39125901, 2024). "Our work consistently connects these findings to humans and provides a rationale for conducting a clinical trial with pharmacological targeting of CCR2 in patients with atherosclerosis." (PMID 37645892, 2024). "In cardiovascular conditions, CCL2 and CCR2 are integral to atherosclerosis, myocardial infarction, and heart failure." (PMID 39201480, 2024). "More recent developments have been made in developing CCR2 agonists to inhibit the development of atherosclerosis." (PMID 39201480, 2024). "Through LASSO analysis, we ultimately identified CCL3, TNF, CCR2, and CCR5 as key genes, which showed high diagnostic value in gout and atherosclerosis through ROC curve analysis." (PMID 39677038, 2024). "In atherosclerosis, the activation of CCR2 promotes monocyte migration to the vascular wall and their transformation into macrophages, participating in plaque formation." (PMID 39677038, 2024). "TLK–19705, a CCR2 antagonist, was tested by Okamoto and colleagues for its impact on atherosclerosis in mouse models of diabetic nephropathy." (PMID 39125901, 2024). "CCL2 signals through its receptor CCR2, which is required for monocyte emigration from the bone marrow during an inflammatory response, and deletion of CCR2 significantly reduces atherosclerosis." (PMID 37200978, 2023). "Of relevance, sulfated proteins include several chemokine receptors (e.g., CCR2, CCR5, CX3CR1) and adhesion molecules (e.g., PSGL1), which are implicated in atherosclerosis." (PMID 37424015, 2023). "C-C motif chemokine receptor 2 (CCR2) is a key factor involved in the accumulation of macrophages during the progression of atherosclerosis." (PMID 38066566, 2023). "Epidemiological and laboratory evidence suggested the correlation and therapeutic potential of CCL2/CCR2 with the pathogenesis of atherosclerosis, and there is increasing evidence that lncRNAs are misregulated in atherosclerosis." (PMID 36872292, 2023). "A recent study reported an increase in intermediate monocytes expressing CCR2 in adults with atherosclerosis." (PMID 36286282, 2022). "The CCL2/CCR2 axis regulates the inflammatory recruitment of classical monocytes in atherosclerosis, as well as in the infarcted heart." (PMID 35743792, 2022). "In murine preclinical models of atherosclerosis, both directed antagonism to either CCR2 or a subset of chemokine receptors, including CCR2, result in a reduction in plaque formation." (PMID 35711383, 2022). "Although increasing evidence in adults indicates that monocyte subsets expressing CCR2 contribute to atherosclerosis in a sex-dependent fashion, there is still scant information on girls and boys with obesity." (PMID 36286282, 2022). "There is powerful proof that chemokine CCL2 and its receptor CCR2 function in cardiovascular diseases such as heart failure, atherosclerosis and coronary atherosclerotic heart disease, hypertension and cardiomyopathy." (PMID 36110847, 2022). "We also observed the downregulation of genes encoding monocyte chemoattractant protein-1 (MCP-1 or CCL2) and its receptor CCR2 that are involved in monocyte/macrophage migration and are found upregulated in atherosclerosis." (PMID 35694160, 2022). "The role of CCR2+ monocyte subpopulations in identifying an abnormally high IMT shows a marked sexual dimorphism, where boys seem to be at higher subclinical atherosclerosis risk than girls." (PMID 36286282, 2022). "Specifically, evidence has shown that blocking MCP-1 and/or its receptor C-C motif chemokine receptor 2 can alleviate atherosclerosis and myocardial infarction." (PMID 35672449, 2022).